EZR (ezrin)
Diseases named in the same sentence as EZR in open-access papers (continued):
Sharing a sentence is not in itself a finding about the gene and the disease.
breast carcinoma (continued). "In this manuscript, we explored the regulatory actions of estrogen on ezrin activity and the effects on breast cancer cell cytoskeleton remodeling, migration and invasion." (PMID 21818323, 2011). "Overall, these findings highlight the relevance of the ezrin activity for breast cancer progression." (PMID 21818323, 2011). "E2 enhances the horizontal cell migration and invasion of T47-D breast cancer cells in three-dimensional matrices, which is reversed by transfection of cells with specific ezrin siRNAs." (PMID 21818323, 2011). "ER-dependent PI3K activation results in the activation of the RhoA/ROCK-2 cascade and through this manner it increases ezrin activity in breast cancer cells." (PMID 21818323, 2011). "In this study, we show that E2 promotes breast cancer cell movement and invasion by the rapid activation of ezrin." (PMID 21818323, 2011). "Treatment with E2 (10−8 M) on T47-D breast cancer cells resulted in a rapid increase of Thr567-phosphorylation of ezrin." (PMID 21818323, 2011). "We also found changes in Ezrin protein expression in breast cancer cells following transfection with miR-183." (PMID 20858276, 2010). "Screening of a broad spectrum of human cancers, including breast, lung and prostate tumors showed high expression of ezrin in tumors of mesenchymal origin and in primary breast carcinomas." (PMID 19680458, 2010). "In breast carcinoma cells, ezrin recruits and interacts with Dbl at the plasma membrane, although in this case this results in activation of Cdc42." (PMID 20939895, 2010). "The assessment of Ezrin expression in breast cancer cells can be both cytoplasmic and membranous, however the differential localization, rather than total Ezrin protein levels is associated with the malignant potential of the cell." (PMID 20858276, 2010). "High-level ezrin expression was observed in many tumor cell lines, such as breast carcinoma and rhabdomyosarcoma cell lines." (PMID 20569470, 2010). "It is likely that much of the migration inhibition induced by miR-183 in breast cancer cells is modulated via Ezrin downregulation." (PMID 20858276, 2010). "Ezrin has been found to be over-expressed in invasive epithelial neoplasia, such as in estrogen-sensitive endometrial and breast carcinomas, and in highly aggressive sarcomas as well, being related in many of these studies to the presence of tumor metastasis." (PMID 18493596, 2008). "Ezrin, another member of the ezrin/radixin/moesin (ERM) family, is over-expressed in highly aggressive sarcomas, as well as in breast cancer, being associated with higher metastasis rate." (PMID 18493596, 2008). "In the present study we show for the first time that ezrin is required for invasion and metastasis of mammary carcinoma cells." (PMID 15987432, 2005). "Our findings indicate that ezrin is required for breast cancer metastasis, and that c-Src and phosphatidylinositol 3-kinase/Akt are effectors of ezrin in the cell motility and invasion stages of the metastatic process." (PMID 15987432, 2005). "Our focus was therefore on the qualitative effects on breast cancer metastasis of blocking ezrin function using a dominant-negative amino-terminal ezrin mutant." (PMID 15987432, 2005). "In the present study we demonstrate for the first time that ezrin function is required for metastasis of breast carcinoma cells." (PMID 15987432, 2005). "We examined the role of ezrin in metastasis using a highly metastatic murine mammary carcinoma cell line, namely AC2M2." (PMID 15987432, 2005). "Our results show that inactivating ezrin function by overexpressing a dominant-negative (amino-terminal) ezrin mutant blocks spontaneous pulmonary metastases of mammary carcinoma cells transplanted into the orthotopic site." (PMID 15987432, 2005). "Indeed, in this report we demonstrate that Erbin co-localizes with and is in close physical proximity to HER2, NHERF1 and Ezrin in breast cancer cells, especially within actin-rich membrane protrusions." (PMID 40390040, 2025).
breast carcinoma (continued). "The co-expression of PTHrP and ezrin may indicate a synergistic role in enhancing breast cancer cells’ invasive and metastatic potential." (PMID 39827339, 2025). "The study highlights the significant roles of PTHrP and ezrin in breast cancer progression." (PMID 39827339, 2025). "Further Western blot analysis showed that silencing ezrin reduced the expression levels of VEGF and HIF1α, while overexpression of ezrin increased these levels, indicating that ezrin may possess pro-angiogenic properties in breast cancer." (PMID 39827339, 2025). "The expression of ezrin in breast cancer patient tumours has been shown in a number of studies, including assessment between normal/benign breast lesions and cancer tissue, and/or associations with clinical outcome; these studies have often resulted in conflicting information." (PMID 36938826, 2023). "Ezrin may prove to be an interesting biomarker in breast cancer and future work should investigate larger, more geographically diverse patient cohorts, including standardisation of cut points." (PMID 36938826, 2023). "In breast cancer cells, Ezrin upregulation correlates with HER2 expression." (PMID 37371090, 2023). "Additional studies assessed ezrin expression in specific breast cancer subgroups." (PMID 36938826, 2023). "This is the largest study to determine ezrin protein expression in breast cancer to date." (PMID 36938826, 2023). "Thus, AJAP1-positive staining was observed in 213 (56.5%) cases of 377 breast cancer samples and Ezrin-positive staining occurred in 165 (43.77%) cases of 377 breast cancer tissue slides." (PMID 35311087, 2022). "AJAP1 depletion might mediate breast cancer malignancy potential through promoting Ezrin expression and cytoskeleton formation." (PMID 35311087, 2022). "As for breast cancer prognosis, high expression of Ezrin predicted poor OS and high DFS." (PMID 35311087, 2022). "Moreover, our report provided the first document to explore the relationship between AJAP1 and Ezrin expression in breast cancer tissue slides and analyzed their expression with clinicopathological parameters." (PMID 35311087, 2022). "In summary, we identified a nine-MRG signature that can be used as an efficient prognostic indicator for breast cancer patients, and owing to its involvement in regulating breast cancer metastasis, EZR might serve as a therapeutic target." (PMID 37304008, 2022). "What is more, Ezrin is also related with breast cancer multidrug resistance." (PMID 35311087, 2022). "Furthermore, while ezrin is expressed in all breast cancer subtypes, expression was highest in ER+ (Luminal A, Luminal B) and HER2+ subtypes at the RNA level, and the highest in Luminal A and B subtypes at the protein level." (PMID 36923551, 2022). "AJAP1 and Ezrin expression with clinicopathological parameters in breast cancer patients." (PMID 35311087, 2022). "Collectively, AJAP1 negatively mediated Ezrin expression in breast cancer cell lines." (PMID 35311087, 2022). "Besides, many reports showed that estrogen E2, CD44, etc., mediated Ezrin to promote the malignant potential of breast cancer." (PMID 35311087, 2022). "More importantly, these results might bring a new insight on the feedback loop of AJAP1 and Ezrin in breast cancer progression." (PMID 35311087, 2022). "Positive staining of Ezrin was mainly observed in the cytoplasm in the breast cancer tissue slides." (PMID 35311087, 2022). "Taken together, these data suggested that there might be a HAS2-Ezrin-ER axis in regulating the acquired antiestrogen resistance of ER+ breast cancer." (PMID 36386154, 2022). "Our findings indicate that ezrin is an important modulator of chemotherapy resistance in breast cancer and that anti-ezrin therapy can sensitize metastatic breast cancer cells to DOX or DTX in preclinical models of neoadjuvant or neoadjuvant plus adjuvant treatment." (PMID 36923551, 2022). "In breast cancer, many reports revealed Ezrin’s different functions." (PMID 35311087, 2022).
breast carcinoma (continued). "Ezrin is a potential prognostic biomarker especially for the recurrence of breast cancer." (PMID 35328667, 2022). "In this study, we examined whether ezrin affects the sensitivity of breast cancer cells to anthracycline or taxanes using both in vitro and in vivo models." (PMID 36923551, 2022). "In fact, the Y477F ezrin mutant reduced the number of lung metastasis events of breast carcinomas." (PMID 35328667, 2022). "AJAP1/Ezrin expression and clinicopathological parameter in patients with breast cancer patients." (PMID 35311087, 2022). "Besides, we also demonstrated a new relationship between AJAP1 and Ezrin in mediating the cytoskeleton of breast cancer cells." (PMID 35311087, 2022). "However, further studies were needed to analyze the concrete pathway between AJAP1-mediated Ezrin activity in prohibiting breast cancer progression and related clinical therapeutic strategies." (PMID 35311087, 2022). "Moreover, High expression of EZR was accompanied with poor overall survival (OS) in breast cancer patients." (PMID 34627255, 2021). "Therefore, extravasation in breast cancer cells appears to rely on PODXL-ezrin interactions, which likely enable cells to polarise and rearrange their cytoskeleton for transendothelial migration." (PMID 34201212, 2021). "Moreover, it was shown to inhibit cell migration by repressing Ezrin gene in breast cancer cell line T47D." (PMID 32040529, 2020). "In other words, KIF14, Mieap, and EZR can be considered as markers of breast cancer invasion." (PMID 32679794, 2020). "Surprisingly, we found that EZR negative expression at the tips of the torpedo-like structures is associated with breast cancer metastasis." (PMID 32679794, 2020). "Ezrin promotes breast cancer progression and enhances metastasis through Akt signaling." (PMID 33240887, 2020). "Complementing the “education” of tumor-associated macrophage gene expression by tumor cells, we show the influence of THP-1 cells on tumor cell chemoattraction, matrigel invasion, and the clonogenic growth of both breast cancer cell lines is in part myeloid cell ezrin-dependent." (PMID 33086476, 2020). "Probably, non-genetic factors may account for changes in the expression of these proteins, because, according to TCGA, KIF14, EZR, and SPATA18 genes are very rarely mutated in breast cancer (less than 1%)." (PMID 32679794, 2020). "Ezrin is involved in tumor-induced angio/lymphangiogenesis in breast cancer cells." (PMID 33171868, 2020). "Recently, ezrin (EZR) proved to promote breast cancer progression by modulating the Akt signaling." (PMID 32545325, 2020). "Our results indicate that the positive expression of KIF14 and Mieap and negative expression of EZR at the tips of the torpedo-like structures is associated with a high frequency of breast cancer metastasis." (PMID 32679794, 2020). "Moreover, ezrin contributes to breast cancer stem cell chemo-resistance, and has been proposed as a prognostic marker." (PMID 33086476, 2020). "Furthermore, we investigated the ezrin protein coded by EZR gene in 120 samples of breast cancer tissue by immunohistochemistry assay and found that the ezrin positive expression in 98 cases was present in 81.7% of all the cases." (PMID 31452341, 2019). "Since resistin consequentially increases ezrin phosphorylation, and ezrin knock-down blocks resistin-induced breast cancer cell invasion, PP2A-mediated ezrin phosphorylation may be a critical regulator of breast cancer metastasis." (PMID 31382374, 2019). "For patients with colorectal cancer, high expression of EZRIN usually can predict a poor survival rate, and some researchers showed that silencing of EZRIN could inhibit the metastasis of breast cancer cells." (PMID 31333725, 2019). "EZR is upregulated in breast cancer and can be used as potential biomarker for overall survival." (PMID 31452341, 2019).
breast carcinoma (continued). "Besides, estrogen-dependent PI3K activation has also been reported to enhance cell motility and invasion by activating the RhoA/ROCK-2 cascade and ezrin activity in breast cancer cells." (PMID 26845172, 2016). "Furthermore, our demonstrated regulatory role of ezrin in the expression of IL-6 is highly relevant as high levels of IL-6 correlate with increased metastatic potential and poor outcome in breast cancer." (PMID 25231728, 2014). "Additionally, ceramide regulates actin cytoskeleton dynamics in breast cancer cells through modulation of ezrin, radixin, moesin function." (PMID 24872355, 2014). "Furthermore, the expression of ezrin Y477F reduced the angio/lymphangiogenic potential of the highly invasive mouse AC2M2 mammary carcinoma cell line." (PMID 25231728, 2014). "Growing evidence suggests ezrin and moesin as novel prognostic markers of disease outcome, although the molecular and cellular basis of their role in breast cancer remains unclear." (PMID 25231728, 2014). "Moreover, miR-183 has been considered a metastatic inhibitor by targeting ezrin and lymph node metastasis in medullary thyroid carcinoma, and this miRNA was recently described as being involved in breast cancer progression." (PMID 25277099, 2014). "The aim of this study was to examine the expression of ERM (ezrin, moesin) and Rho (RhoA, RhoB and Cdc42) proteins in breast cancer (BC) patients and to investigate the relationship between the sub-cellular localisation of these proteins and clinicopathological characteristics and patient survival." (PMID 23420497, 2013). "While these clinical data indicate that plasma membrane p-ezrin expression is related overall to a more aggressive phenotype of breast cancer, the mechanism(s) involved in its role as a metastasis promoter are unknown." (PMID 24086451, 2013). "Ezrin protein expression was detected in all breast cancer (BC) cases with a mean IRS of 8.88." (PMID 23420497, 2013). "Furthermore, suppression of ezrin function using shRNA and dominant negative ezrin mutants abrogates invasion, early metastatic survival, as well as lung metastases in osteosarcoma, rhabdomyosarcoma, and breast carcinoma cell lines." (PMID 22397367, 2012). "Recent publications showed that Ezrin is strongly expressed in a variety of invasive cancers, including osteosarcoma, melanoma, soft tissue sarcoma, pancreatic carcinoma, hepatocellular carcinoma and gastric and breast cancers." (PMID 23039327, 2012). "Interestingly, c-Src/PI3K can also function as the downstream cascade of ezrin to maintain cell survival or to promote breast cancer metastasis." (PMID 21818323, 2011). "Moreover, Akt is believed to govern breast cancer metastasis, which is partly due to its modulation on ezrin phosphorylation and localization." (PMID 21818323, 2011). "The active ezrin is also capable to recruit the guanine nucleotide exchange factor Dbl to lipid rafts and preferentially activates Cdc42, which is important for directional breast cancer cell migration." (PMID 21818323, 2011). "In conclusion, E2 promotes breast cancer cell movement and invasion by the activation of ezrin." (PMID 21818323, 2011). "The identification of ezrin regulation may thus offer important mechanistic insights to breast cancer metastasis." (PMID 21818323, 2011). "Likewise, in ER/PR positive MCF-7 breast cancer cells, E2 also provoked the rapid phosphorylation of ezrin on Thr567, suggesting that this action is generalized rather than cell specific." (PMID 21818323, 2011). "Moreover, the overexpression of wild-type ezrin is shown to promote breast cancer metastasis in animal model experiment." (PMID 21818323, 2011). "Finally we observed the role of ezrin activation in estrogen-sensitive breast cancer cell migration and invasion." (PMID 21818323, 2011). "Ezrin silencing by small hairpin RNA could reverse the metastatic behavior of human breast cancer cells." (PMID 20569470, 2010).
breast carcinoma (continued). "Together, these results suggest that blocking ezrin function may represent a novel and effective strategy for preventing breast cancer metastasis." (PMID 15987432, 2005). "Together, our findings suggest that ezrin activation may represent an effective prognostic marker and a potential target for treatment of invasion and metastasis of human breast cancer." (PMID 15987432, 2005). "However, the role of ezrin in breast cancer chemoresistance is not fully known." (PMID 36923551, 2022). "However, regression analyses suggest a stronger correlation between ezrin levels and NSC sensitivity compared with radixin in breast cancer cells and that breast cancer cells may be more dependent on ezrin function over other ERMs." (PMID 36923551, 2022). "However, more data on the mechanism of Ezrin in breast cancer need to be further explored." (PMID 35311087, 2022). "Moreover, silencing of Ezrin reduced the ability of breast cancer cell motion and invasion." (PMID 35311087, 2022). "Similarly, another study that reported antimetastatic properties of NSC668394 in breast cancer showed that ezrin-deficient cells treated with NSC668394 no longer showed reduced migration." (PMID 33005093, 2020). "Additionally, miR-200b and miR-200c could suppress migration and invasion of breast cancer cells by regulating ezrin-radixin-moesin and fucosyltransferase-4." (PMID 31488193, 2019). "However, the possible involvement of Ezrin in metastasis and angiogenesis in breast cancer remains unclear." (PMID 30804430, 2019). "Notably, ezrin has been shown to colocalize with MUC1 in breast carcinomas." (PMID 28588132, 2017). "For example, SIX1 induces epithelial-to-mesenchymal transition (EMT) in breast cancer cells by activating transcription of the gene encoding the TGF-β type I receptor and promotes metastasis of rhabdomyosarcoma by inducing expression of the cytoskeletal protein ezrin." (PMID 25023983, 2014). "The potential involvement of HGF/Met in Src/ezrin-mediated tumour angio/lymphangiogenesis is consistent with our recent finding demonstrating Src/ezrin co-operation increased Met activation and extracellular matrix degradation, characteristic of an invasive phenotype in breast cancer." (PMID 25231728, 2014). "Furthermore, ezrin is essential in experimental invasion and metastasis models of breast cancer." (PMID 25231728, 2014). "Migrating GFP-MCAM WM239a cells were morphologically similar to rounded MDA-MB-231 breast carcinoma cells that were previously characterized by cortical F-actin flow towards a pronounced uropod-like structure and A375 melanoma cells that expressed an “ezrin-rich uropod-like structure (ERULS)." (PMID 24349113, 2013). "In this study, we investigated the expression of the ERM (ezrin, moesin) and Rho (RhoA, RhoB, Cdc42) protein families in a homogeneous group of patients with stage II invasive ductal breast cancer (BC)." (PMID 23420497, 2013). "Therefore, our study implicates a unique role of Src/ezrin in regulating local invasion of breast carcinoma cells, and provides a clinically relevant model for assessing the potential of this pathway as a prognostic biomarker or a predictive marker for treatment response or relapse." (PMID 22397367, 2012). "Moreover, increased cytoplasmic expression of ezrin is frequently associated with dedifferentiation, invasiveness, and poor prognosis in human breast cancers; compared to membranous apical expression in non-malignant epithelial tissues." (PMID 22397367, 2012). "Thus expression of Y477F ezrin attenuates migration of confluent breast carcinoma cells." (PMID 22397367, 2012). "In summary, in breast cancer cells, Erbin interacts with HER2 as well as other scaffolding proteins, including NHERF1 and Ezrin." (PMID 40390040, 2025). "Together, these findings suggest that the expression of HER2 combined with the loss of cell polarity facilitate physical interactions between Erbin, NHERF1, Ezrin and HER2 in breast cancer cells." (PMID 40390040, 2025).